CD34 (CD34 molecule)
Diseases named in the same sentence as CD34 in open-access papers (continued):
Sharing a sentence is not in itself a finding about the gene and the disease.
type 2 diabetes (25 papers, 2011 to 2025). "In observational studies of people with type 2 diabetes, the count of CD34+KDR+ cells negatively correlated with the severity of diabetic complications, meaning fewer cells were associated with more severe disease." (PMID 41009758, 2025). "In our research, we demonstrated that smokers and patients with type II diabetes have a significantly reduced number of CD34+ cells in peripheral blood in basal conditions." (PMID 37895025, 2023). "Canagliflozin when added to subjects with Type 2 Diabetes along with metformin and/or Insulin, demonstrates a functional improvement of CD34+ Endothelial Progenitor Cell migratory function through increased CD34/CXCR4 positivity." (PMID 33581737, 2021). "Low dose Canagliflozin has a beneficial effect on CD34+ cell function, serum biochemistry and urinary podocyte specific exosomes in type 2 diabetes." (PMID 33581737, 2021). "It has been reported that CD34+ cells from patients with type 2 diabetes have defective chemotaxis to SDF-1α resulting in reduced vasculogenic potential." (PMID 29724198, 2018). "This delivery route has been used to inject hematopoietic stem cells (CD34+) into patients with type 2 diabetes, improving metabolic control with reduction of insulin requirements." (PMID 25884215, 2015). "Having documented the presence of structural and functional nociceptive alterations in the BM of patients with type 2 diabetes, we next conducted immunofluorescence and flow cytometry analyses of CD34+ HSPCs, which co-express the SP receptor NK1R." (PMID 26358583, 2015). "CD34+ cells represent an ideal biomarker for the prediction of the cardiovascular disease, metabolic syndrome and type 2 diabetes." (PMID 24223881, 2013). "Moreover, a longitudinal study of 187 patients with type 2 diabetes reported that a reduced baseline level of CD34+ cells predicted microvascular outcomes after a mean follow‐up of 3.9 years." (PMID 40276845, 2025). "Similarly, TSP-1-derived peptide RFYVVMWK improved the adhesive phenotype of CD34 positive cells from atherosclerotic patients with type 2 diabetes." (PMID 30720765, 2019). "Literature data show that intravenous infusion of rHDLs stimulates EPC differentiation and recruitment in rodents, exerts beneficial effects on circulating CD34+ cells in patients with recent acute coronary syndrome and increases circulating CD34+/VEGFR2+ cells in patients with type 2 diabetes." (PMID 29866130, 2018). "In a very recent paper, a mid-term (4-month) treatment with sitagliptin was associated with a significant increase in EPCs -phenotypically characterised as CD34+/CXCR-4+ cells- in 30 patients with type 2 diabetes in poor glucose control with metformin and/or sulphonylurea." (PMID 28231835, 2017). "Lee and colleagues evaluated, in a cross-sectional study, the concentration of circulating EPCs, defined as CD34+ cells or c-Kit+ cells, in a group of 45 type 2 diabetic patients and compared them with those observed in 15 age- and gender-matched control subjects." (PMID 24782825, 2014). "Indeed, for example, although TNF-α is required for DCs generation from CD34 + precursors, its increased production by monocytes in type 2 diabetes with CAD may adversely affect blood DC differentiation from CD34 + precursors." (PMID 21658276, 2011). "In this study we show for the first time that saxagliptin, in addition to metformin, positively modulates CD34+ EPCs, as a marker of vascular endothelial function, in early onset type 2 diabetes subjects who have no overt cardiovascular complications." (PMID 29724198, 2018). "We conclude that CD34+ cell function improves post saxagliptin therapy compared to a matched placebo in an early onset type 2 diabetes population that did not have any known cardiovascular disease or complications." (PMID 29724198, 2018).
type 2 diabetes (continued). "Since individuals with type 2 diabetes have CD34+ cells expressing high levels of PAI-1, their CD34+ cells theoretically will benefit from having levels of PAI-1 reduced toward a normal, non-diabetic range prior to the use of these cells as an autologous cell therapy." (PMID 24223881, 2013). "Combination therapy adding the dipeptidyl peptidase-4 (DPP-4) inhibitor, saxigliptin to concurrent metformin therapy for 12 weeks was found to increase CD31+ numbers (reflecting a mature circulating pool of endothelial cells) but not CD34+ in type II diabetes patients." (PMID 35909294, 2023). "The first evidence indicated that a 4-week treatment with sitagliptin increased circulating EPC number (CD34+ and KDR+ cells) in a non-randomised study conducted in a small group of patients with type 2 diabetes." (PMID 28231835, 2017). "In particular, the presence of ischaemia, which reportedly acts as a potent stimulus for CD34+NK1R+ HSPC release, fails to promote cell mobilisation in patients with type 2 diabetes." (PMID 26358583, 2015). "To confirm the presence of a specific form of mobilopathy affecting the subpopulation of CD34+NK1R+ HSPCs, we investigated an independent cohort of 24 non-diabetic individuals and 74 patients with type 2 diabetes." (PMID 26358583, 2015).
fibrosarcoma (24 papers, 2011 to 2026). A malignant mesenchymal fibroblastic neoplasm affecting the soft tissue and bone. "Other notable targets being investigated in the STS realm include NTRK fusion in CD34-positive fibrosarcomas of bone and soft tissue, EZH2/INI1 loss (epithelioid sarcomas, rhabdoid tumors), and ALK fusion in inflammatory myofibroblastic tumors." (PMID 40075735, 2025). "The visceral NTRK-RSCNs mainly exhibited high-grade morphology such as MPNST/fibrosarcoma-like, characterized by co-expression of CD34, S100, and pan-TRK." (PMID 40548109, 2025). "In addition, presence of atypia in fibrosarcoma, cellularity, CD34 positivity in phyllodes tumors, and cleft-like structures covered with epithelium are clues for the differential diagnosis." (PMID 26558181, 2015). "Moreover, myxoid fibrosarcoma usually lacks strong CD34 expression." (PMID 23148444, 2012). "Research has shown that the regions with FS change in individuals who have lost CD34 immunoreactivity, possibly in line with the development of CD34-negative fibrosarcoma." (PMID 39634408, 2024). "In addition, CD34 expression was also lost in the tumor tissue of a recurrent DFSP patient with myxoid and fibrosarcoma changes." (PMID 39634408, 2024). "CD34 has been considered a vital marker for DFSP and can be used to differentiate DFSP of the breast from CD34-negative fibrous soft tissue tumors, such as dermatofibromas, breast fibroadenomas, and fibrosarcomas." (PMID 33224981, 2020). "Immunohistochemical staining for CD34 is negative, and 80 % of the cases are positive for nuclear beta-catenin; however, spindle cell carcinoma, phyllodes tumors, and fibrosarcoma could also be positive." (PMID 26558181, 2015). "Histopathology showed low-grade fibrosarcoma; immunohistochemistry was positive for Vimentin and SMA, focally CD34, and negative for S100, Desmin, and Myogenin, with low Ki-67 (<3 %)." (PMID 41045685, 2025). "Immunohistochemically, spindle cells typically show strong and diffuse cytoplasmic expression of CD34 in classical DFSP, whereas in fibrosarcoma DFSP, CD34 often expresses weakly positive or negative." (PMID 40304095, 2025). "These infantile fibrosarcomas were diffusely and robustly positive for Trk (100%), S100 protein (50%, 3/6 cases), nestin, CD10 (80%, 4/5 cases), and vimentin (100%), but negative for CD34, SMA, desmin, myogenin, and CD56." (PMID 32957984, 2020). "Consistent with the immunophenotypic profile of low-grade malignant fibrosarcoma, only Vimentin is expressed in immunohistochemistry; SMA may show positive expression in instances of myofibroblastic differentiation; Desmin, CK, EMA, and CD34 were non-reactive." (PMID 39968290, 2024).
graft versus host disease (23 papers, 2014 to 2026). An immune system disorder that occurs after allogeneic hematopoietic stem cell transplant and is a reaction of donor immune cells against host tissues. "We investigated the effect of cytomegalovirus (CMV) serostatus on the involvement of HPSE enhancer and insulator functional SNPs in the risk of acute graft versus host disease (GVHD) and granulocyte-colony stimulating factor related CD34+ mobilization." (PMID 34943994, 2021). "When compared to DLI, a CD34 SCB is associated with decreased risk of graft versus host disease (GvHD) and, hence, may be the preferred intervention to improve GF or DC." (PMID 37027103, 2023). "Compared with the humanized mice using CD34+ hematopoietic stem cells (HSCs), the humanized model constructed by peripheral blood mononuclear cells (PBMCs) takes less time, but graft versus-host disease (GvHD) occurs." (PMID 36072895, 2022). "The most common risk factors for post-HSCT thrombocytopenia are disease remission status, amount of infused CD34+ cells, graft-versus-host disease (GVHD), stem cell source, cytomegalovirus (CMV) infection, and drugs." (PMID 36161632, 2022). "Haplo-HSCT became feasible in the 1990s by intensifying the conditioning regimen to prevent graft rejection, and by the infusion of “megadoses” of CD34+ purified cells, thus depleting T cells responsible of the occurrence of graft-versus-host disease (GvHD)." (PMID 32764469, 2020). "Among these, a multicenter prospective study of 932 recipients of unrelated donor peripheral blood stem cells (PBSCs) found higher doses of CD34+ cells resulted in rapid engraftment and improved OS without increased risk of graft-versus-host disease (GVHD)." (PMID 40723206, 2025). "Following myeloablative conditioning with total body irradiation (TBI, 12 Gy) and melphalan (140 mg/m2), donor peripheral blood stem cells (3.3 × 106/kg of CD34-positive cells) were infused with graft-versus-host disease (GVHD) prophylaxis using tacrolimus and short-course methotrexate." (PMID 40478404, 2025). "The current state and future directions for donor selection (sex, age, ABO blood type, and HLA disparity), donor source, the dose of infused CD34+ cells, optimal conditioning, and the concomitant graft-versus-host disease prophylaxis other than PTCY are also extensively discussed." (PMID 38339351, 2024). "Similarly, murine MSCs with CD73+ and CD34+ EVs have been shown to reverse graft-versus-host disease (GvHD) and hindlimb ischemia by suppressing Th1-mediated inflammation." (PMID 35399522, 2022). "Furthermore, it has been noted that the composition of graft cells, specifically the ratio of CD34+ HSCs to CD3+ T-cells, can significantly impact the success of engraftment and the incidence of graft-versus-host disease (GVHD)." (PMID 41561246, 2025). "However, CD3+ T cells, which were present in the transplanted CD34-negative cell fraction of patient II-2, expanded over the course of 90 days under placebo treatment leading to a clinically inapparent graft-versus-host disease." (PMID 26546739, 2015). "One case report describes how a patient who received CD34+ cells (8 × 106/kg body weight) on day14 after kidney transplantation, showed neither kidney rejection nor clinical manifestations of graft-versus-host disease (GVHD) during a follow-up for of more than 2 years." (PMID 25364716, 2014). "To address this major limitation, we have developed an improved humanized mouse model, derived from fresh CD34+ stem cell engraftment in NOD.Cg-PrkdcscidIl2rgtm1Wjl/SzJ (NSG) mice, without the onset of graft-versus-host disease (GVHD)." (PMID 35210547, 2022).
soft tissue tumors (22 papers, 2014 to 2026). "Among ALK-related tumors, superficial ALK-rearranged myxoid spindle cell neoplasm (SAMS) is a rare, soft tissue tumor characterized by the immunophenotypical co-expression of CD34 and S100." (PMID 39202049, 2024). "Considering immunohistochemistry, CD34 expression is a consistent finding; however, it can be positive in other types of soft tissue tumors." (PMID 39551910, 2024). "Among soft tissue tumors with CD34 and S100 expression, neurofibroma and malignant peripheral nerve sheath tumor (MPNST) are the main differential diagnosis." (PMID 36229858, 2022). "Based on the clinicopathologic and genomic features of the two cases, RAF 1 fusion-positive soft tissue tumor with S100 and CD34 co-expression was the final diagnosis." (PMID 36229858, 2022). "We considered that both patients had a low-grade soft tissue tumor with S100 and CD34 co-expression." (PMID 36229858, 2022). "Particularly among other CD34 positive tumours, STAT6 is a useful SFT diagnostic marker due to the NAB2-STAT6 fusion in SFTs and some other soft tissue tumours, such as dedifferentiated liposarcoma express STAT6." (PMID 32566457, 2020). "In addition to IMT, receptor tyrosine kinase gene fusion has been reported in a variety of soft tissue neoplasms, such as S100/CD34-positive spindle cell mesenchymal neoplasm." (PMID 37735390, 2023). "CD34 is a cell surface glycoprotein and is expressed on hematopoietic cells, mesenchymal stem cells, endothelial progenitor cells, endothelial cells of blood vessels, mast cells, dendritic cells, and some soft tissue tumors." (PMID 36553048, 2022). "Other markers, such CD34, CD117, myogenin, and DOG1 (discovered on GIST, also known as anoctamin 1), have also been proposed to play a significant role in identifying soft tissue tumors." (PMID 41262926, 2025). "Immunohistochemically, these tumors appear to express endothelial markers such as EGR, CD31, CD34, F VIII-Rag, which are usually expressed by EHE as well as other types of vascular or soft-tissue tumors, indicating that these markers have poor specificity." (PMID 35347504, 2022). "CD34 is expressed significantly in a large number of soft tissue neoplasms and many entities that are included in the differential diagnosis of SFT, such as PSS and GIST, share CD34 expression." (PMID 28687087, 2017). "Recently, a series of low to intermediate grades of soft tissue tumors showing recurrent fusions involving RAF1, BRAF, and NTRK1/2 genes have been defined as a new entity with S100 and CD34 co-expression (without SOX-10 positivity)." (PMID 36229858, 2022).
liver fibrosis (21 papers, 2015 to 2025). "Key molecules associated with liver fibrosis and inflammation (Cd34, Epcam, S100a6, Fhl2, Itgax, and Retnlg) were up-regulated at both the gene and protein levels." (PMID 38076459, 2023). "Masson and CD34 staining showed increased liver fibrosis and micro-vessel in HBV; Pten−/− livers (p < 0.001)." (PMID 38459588, 2024). "Newly formed CD34+ intrahepatic vessels were increased alongside liver fibrosis in CCl4-treated rats, indicating the development of sinusoidal capillarization." (PMID 38534382, 2024). "Newly formed CD34‐positive intrahepatic vessels were mildly increased by CCl4 administration for two weeks at the start of the lenvatinib treatment along with liver fibrosis." (PMID 33609067, 2021). "Yet, one has to consider that aberrant Apln expression is also found in CD34+ capillarized LSECs in liver fibrosis and cirrhosis and also pro-angiogenic effects were similar to the vascular apelin signaling." (PMID 34658910, 2021). "The inhibition of integrin αvβ3 and αvβ5 disturbed the engraftment of transplanted CD34+ cells and aggravated liver fibrosis." (PMID 27162932, 2016). "Moreover, CD34-positive cell transplantation improves hepatic fibrosis by promoting intrahepatic angiogenesis and supplying various growth factors." (PMID 40136677, 2025). "The terminal differentiation marker Cd209b of LSECs was significantly downregulated in all three groups of liver fibrosis models, whereas the capillarization marker gene Cd34 and the Edn1 receptor Ednrb of LSECs were significantly upregulated in all three groups of liver fibrosis models." (PMID 39194690, 2024). "Expanded CD34+ cell transplantation reduced liver fibrosis, with a decrease of αSMA+ cells." (PMID 27162932, 2016). "In cohorts of 37 and 39 patients, higher CD34 staining has been described in patients with MASH as compared with MASL,25,42 further increasing with the stage of liver fibrosis." (PMID 40486133, 2025). "The goal of this research was to evaluate the relationship among CD34 + HPSCs, SDF-1α, and CXCR4 receptor expression with the percentage of the area of hepatic fibrosis." (PMID 37730560, 2023). "An improved understanding of the different events that occur throughout the process of liver fibrosis and its reversibility; SDF-1α in the bone marrow and liver, and CD34 + cells in the liver and the blood can illuminate our understanding of this process." (PMID 37730560, 2023). "In conclusion, in the CCl4 rat model, there was a substantial correlation between the changes in fibrosis area percentage and the changes in CD34+, SDF-1α, and CXCR4 during the process of liver fibrosis treatment and also during the spontaneous recovery period." (PMID 37730560, 2023). "CD34 is an endothelial adhesion molecule, which is not expressed on normal LSECs but is usually viewed as a capillarization marker in liver fibrosis." (PMID 33535174, 2021). "As we and many others have reported, here we used four different double labelling immunofluorescence methods to analyse the changes in TCs in human liver fibrosis, including double labelling for CD34 and PDGFR-α, CD34 and PDGFR-β, CD34 and vimentin, and CD34 and c-kit/CD117." (PMID 25661250, 2015). "The expression of Cd34 and the numbers of CD34+ cells were increased in the livers of CflarLKO mice fed the CDE diet and wild-type mice fed the CDAHFD diet, suggesting that the expansion of CD34+ cells is not specific to Fgf18 Tg mice but a more generalized phenomenon in liver fibrosis." (PMID 37813881, 2023).